EGFR (epidermal growth factor receptor)
Diseases named in the same sentence as EGFR in open-access papers (continued):
Sharing a sentence is not in itself a finding about the gene and the disease.
lung cancer (continued). "For EGFR-mutated lung cancer, ML-optimized NPs (ML-NPs) were used to deliver both EGFR inhibitors and mRNA vaccines to neoantigens." (PMID 40688030, 2025). "Of note, JBJ-04-125-02 showed synergy with osimertinib, thus suggesting a potential benefit of combination therapies entailing an allosteric inhibitor and an ATP-competitive inhibitor for EGFR-mutated lung cancer." (PMID 40243603, 2025). "The EGFR-TKIs (epidermal growth factor receptor-tyrosine kinases inhibitors) have emerged as an effective therapeutic approach for lung cancer patients with EGFR mutations." (PMID 39744423, 2025). "In exon 21, the L858R point mutation, which substitutes leucine 858 with arginine, is the most prevalent EGFR mutation in lung cancer, accounting for around 40% of all cases, but it is rarely seen in HNSCC." (PMID 40864738, 2025). "Collectively, these data establish lineage plasticity as a fundamental property of EGFR-mutant lung cancers, predisposing AT2-derived tumors to adopt neuroendocrine features under defined genetic or therapeutic pressures." (PMID 41516316, 2025). "This article reviews the latest treatment options for patients with EGFR-mutated lung cancer, discusses how to select the best first-line treatment, and explores what to do once there is cancer progression after first-line treatment." (PMID 40862817, 2025). "Germline genetic mutation of epidermal growth factor receptor (EGFR) T790 M were identified in families with high density of lung cancer cases." (PMID 40831928, 2025). "Oncologists should recognize that EGFR-mutated lung cancer can recur after an exceptionally long disease-free interval through rare metastatic patterns such as tumor-to-tumor metastasis." (PMID 41416296, 2025). "Tepotinib is another MET TKI that is currently being investigated, in combination with osimertinib, in patients with EGFR-mutated lung cancer who acquired MET amplification after progressing to osimertinib." (PMID 40243603, 2025). "In contrast, TERT p.C228T mutations and EGFR mutations (p.L858R and E746_A750del) were exclusive to liver and lung cancer, respectively." (PMID 39748775, 2025). "Genetic mutations on drug targets reduce drug binding (e.g., EGFR mutations in lung cancer resist TKIs like erlotinib) and avoid cytotoxic attacks, enabling continued proliferation." (PMID 40183077, 2025). "For validation, we selected EGFR mutations, which are the most frequently detected in Japanese lung cancer patients." (PMID 40616301, 2025). "In lung cancer cells harboring K-ras mutations and EGFR L858R/T790M mutations, the knockdown of ELF3 significantly increases cell apoptosis." (PMID 40429988, 2025). "The existence of disparate lung cancer subtypes and somatic mutations (e.g., epidermal growth factor receptor (EGFR) alterations) is indicative of geographic disparities in smoking patterns, environmental exposures, and genetics." (PMID 40006082, 2025). "Environmental factors were reported to be associated with the EGFR‐driven lung cancer, whereby the levels of an air pollutant, particulate matter 2.5 (PM2.5), were associated with higher incidences of this cancer subtype." (PMID 41213866, 2025). "The common targets were mapped to lung cancer associated signaling pathways, revealing EGFR as a highly modulated node." (PMID 41449180, 2025). "There is a higher probability of being a long-term survivor among patients with advanced lung cancer and mutations in the EGFR molecular target." (PMID 40255426, 2025). "Epidermal growth factor receptor (EGFR) is the most common driver gene in lung cancer, and its mutation is associated with an increased incidence of BM." (PMID 40172035, 2025). "Conversely, epidermal growth factor receptor (EGFR) mutated non–small cell lung cancers can be particularly sensitive to the induction of ferroptosis after cystine depletion." (PMID 40961184, 2025).
lung cancer (continued). "Radiomic features of another less-used imaging modality in lung cancer—that of MRI for brain metastases—have also been used to predict specific genetic mutations, such as EGFR, ALK, and KRAS, with AUC of over 0.9, as well as OS." (PMID 40075729, 2025). "This can be explained by the fact that the lung cancer cases in the TCGA dataset include a heterogeneous mixture of mutations, with EGFR mutations likely comprising only a small subset and only a small subset of TCGA cases were treated with EGFR-TKIs." (PMID 41281943, 2025). "Overall, EGFR inhibitors have dominated the prescription volume due to the higher prevalence of EGFR mutations in lung cancer." (PMID 41282618, 2025). "We treated the HER2‐amplified SKBR3 breast cancer line with lapatinib and the EGFR‐mutated HCC827 lung cancer line with erlotinib and combined those treatments with AXL inhibitors." (PMID 39395205, 2025). "Reports suggest that Asians with lung cancer show a higher prevalence of tumor‐associated EGFR mutation." (PMID 39757012, 2025). "EGFR, frequently mutated in lung cancers, serves as a pivotal driver of cancer growth and contributes to resistance against targeted anticancer drugs." (PMID 40347254, 2025). "This nonrandomized clinical trial evaluates the activity and safety of high-dose aumolertinib in patients with untreated EGFR-variant non–small cell lung cancer and brain metastases." (PMID 40569623, 2025). "Lastly, osimertinib is a third-generation EGFR tyrosine kinase inhibitor designed to target T790M resistance mutations in nonsmall-cell lung cancer." (PMID 41325773, 2025). "Our data indicated that hypertriglyceridemia and higher HDL cholesterol levels were associated with a lower incidence of EGFR-mutated lung cancer." (PMID 39883280, 2025). "Epidermal growth factor receptor (EGFR) mutations are among the most common oncogenic drivers in non‐small cell lung cancer (NSCLC), particularly in Asian populations and non‐smokers." (PMID 41139406, 2025). "EGFR-mutated non-small cell lung cancer (NSCLC) is a common form of lung cancer that is treated with targeted drugs." (PMID 40862817, 2025). "EGFR mutation screening in non–small cell lung cancer (NSCLC) remains variable globally and represents a significant care gap despite international recommendations and molecular testing guidelines." (PMID 41211715, 2025). "Lung cancer organoid technology now allows systematic generation of patient-derived organoids carrying diverse EGFR mutations, including those emerging before or after osimertinib resistance." (PMID 41425254, 2025). "In radon-induced lung cancer, EGFR is often mutated and overexpressed, leading to the activation of downstream signaling pathways that promote tumor growth and survival." (PMID 40427695, 2025). "For example, acquired resistance to first and second-generation EGFR inhibitors in lung cancer can be conferred by point mutations such EGFR T790M mutation and resistance to third-generation EGFR inhibitors can be conferred by EGFR C797S mutation." (PMID 40649216, 2025). "To confirm our findings in the human system, we used the human lung cancer cell line HCC827 with exon 19 deletion in EGFR, which is an activating mutation that results in excess EGFR expression." (PMID 39948411, 2025). "In the case of lung cancer, the association of EGFR mutations within Asian races has been extensively documented." (PMID 40283044, 2025). "For example, overexpression of the protein epidermal growth factor receptor (EGFR) has been linked to poor prognosis in lung cancer patients." (PMID 40427695, 2025).
lung cancer (continued). "More studies are needed to elucidate if this HER2-targeting ADC is beneficial in the context of EGFR-mutated lung cancer." (PMID 40243603, 2025). "Data on risk factors associated with lung cancers with specific mutations such as EGFR were also unavailable in this review." (PMID 41278400, 2025). "The primary tumor was subjected to a genomic analysis with the AmoyDx Pan Lung Cancer PCR panel, which revealed an EGFR mutation (exon 21 L858R)." (PMID 40620186, 2025). "In recent years, new treatments called tyrosine kinase inhibitors (TKIs) have been developed to target specific genetic mutations in lung cancer, such as EGFR and ALK." (PMID 41149462, 2025). "Human epidermal growth factor receptor 3 (HER3) is a protein known to be hyper-expressed in EGFR-mutated lung cancer and a mediator of resistance to tyrosine kinase inhibitors (TKIs)." (PMID 40805219, 2025). "Mutations of epidermal growth factor receptor (EGFR) are the primary therapeutic targets in non‐small cell lung cancer (NSCLC)." (PMID 39727229, 2025). "In lung cancer, multiple mutations in EGFR are rare, including bilateral synchronous NSCLC characterized by two primary lung tumors." (PMID 40855618, 2025). "Epidermal growth factor receptor tyrosine kinase inhibitors (EGFR‐TKIs) have shown significant efficacy in patients with brain metastases (BMs) from EGFR‐mutated non‐small cell lung cancer (NSCLC)." (PMID 40421655, 2025). "Mutations in the EGFR gene play a pivotal role in the development and progression of lung cancer, particularly in NSCLC, the most prevalent histological subtype." (PMID 41373464, 2025). "This study aims to isolate and characterize EVs released by PC9 lung cancer cells (harboring an EGFR deletion mutation in exon 19 (2235-2257C)) and A549 lung cancer cells (wild-type EGFR)." (PMID 40210802, 2025). "First-generation EGFR inhibitors, such as gefitinib and erlotinib, exhibit activity in patients with non–small cell lung cancers (NSCLC) harboring activating mutations in EGFR." (PMID 40323013, 2025). "H1975 is a human non-small cell lung cancer (NSCLC) adenocarcinoma cell line characterized by concurrent EGFR L858R and T790M mutations, and is widely employed in studies of targeted therapy efficacy and mechanisms of drug resistance in lung cancer." (PMID 41424870, 2025). "This cell line provides a unique model that better aligns with clinical settings and offers distinct advantages in investigating targeted resistance mechanisms in EGFR‐mutated lung cancer brain metastases." (PMID 40172035, 2025). "Mutations in epidermal growth factor receptor (EGFR) are the key drivers of lung cancer initiation and recurrence." (PMID 40479551, 2025). "Previous studies have reported EGFR mutation rates in young lung cancer ranging from 32% to 46.9%, and ALK rearrangement rates from 6.3% to 19%, which are consistent with those reported in this study." (PMID 41002559, 2025). "A total of 200 patients with non‐small cell lung cancer harboring the EGFR L858R mutation were enrolled." (PMID 41308037, 2025). "Further studies have investigated the combination of Alisertib with the third-generation Epidermal Growth Factor Receptor (EGFR) tyrosine kinase inhibitor osimertinib in EGFR-mutated lung cancer." (PMID 39858036, 2025). "We subsequently sought to analyze other tumor types in the pan-cancer FMI databank, due to the already known association between EGFR mutations and lung cancer in this population." (PMID 41162424, 2025). "AKT1 regulates cell proliferation, survival, and metabolism, while mutations in EGFR increase lung cancer sensitivity to tyrosine kinase inhibitor therapy." (PMID 39796173, 2025).
lung cancer (continued). "The AURA and FLAURA trials displayed the superiority of the third-generation TKI in both first- and second-line settings, making it the drug of choice for treating patients with EGFR-mutated lung cancer." (PMID 40243603, 2025). "Amivantamab was first approved by the FDA in 2021 for patients with lung cancer carrying exon 20 insertion mutations in EGFR after the failure of chemotherapy." (PMID 40243603, 2025). "In a previous report on EGFR mutation-positive lung cancers with bone metastasis, 84 % of the cases were osteolytic bone metastases, while osteoblastic bone metastases were less common." (PMID 40104434, 2025). "Lung cancer patients with T790M-negative EGFR mutations were more likely to benefit from nivolumab treatment." (PMID 41162774, 2025). "EGFR TKIs have demonstrated efficacy in managing EGFR-mutated lung cancer after several years of usage." (PMID 40728967, 2025). "The third-generation EGFR TKI osimertinib has greatly improved the management of patients with lung cancer driven by EGFR activating mutations, both as first- and second-line therapy." (PMID 40243603, 2025). "Key findings demonstrated correlations between PET-derived radiomic features and genomic alterations, such as KRAS, EGFR, and TGFβ mutations in lung cancer, and prognostic biomarkers in other malignancies." (PMID 40192792, 2025). "The development of TKI (tyrosine kinase inhibitors) drugs targeting EGFR (epidermal growth factor receptor)-activating mutations has brought lung cancer treatment into the targeted era." (PMID 40732366, 2025). "The International Association for the Study of Lung Cancer recommends, at a minimum, testing for EGFR, ALK, and ROS1." (PMID 41153394, 2025). "Collectively, our results demonstrate that PYCR1 is a key regulator of lung cancer progression and is functionally linked to both EGFR and TLR signaling pathways." (PMID 41254241, 2025). "A landmark 2023 study identified an association between PM2.5 exposure and incidence of EGFR-driven lung cancer." (PMID 40185876, 2025). "The challenge remains in subtypes of lung cancer patients that harbor driver mutations like EGFR, ALK, and ROS1 mutations." (PMID 39932765, 2025). "For example, in lung cancer, common targets include EGFR mutations, ALK gene rearrangements, and other oncogene‐driven changes, such as ROS1, BRAF, NTRK, MET, and KRAS." (PMID 40347011, 2025). "Over the past two decades, the importance of EGFR expression and mutations in lung cancer has been validated, and genomic medicine has led to improved treatments for patients with EGFR-mutated lung cancer." (PMID 41228367, 2025). "The provision of treatment for epidermal growth factor receptor (EGFR)‐mutated nonsmall cell lung cancer (NSCLC) patients has increased in Korea." (PMID 39757012, 2025). "Unfortunately, when the IGF1R inhibitor linsitinib was combined with erlotinib in EGFR-mutated lung cancer patients, the PFS, ORR, and disease control rate were lower in the combination group compared to the erlotinib monotherapy group." (PMID 40243603, 2025). "Studies confirm VDR overexpression in lung cancer and its association with poor prognosis in EGFR-mutated NSCLC patients." (PMID 40872626, 2025). "Lung cancer BM, for instance, frequently retains genetic alterations characteristic of the primary lung cancer, such as EGFR mutations and ALK rearrangements observed in non-small cell lung cancer." (PMID 39857798, 2025). "We identified that BRG1 mutation influenced the response to EGFR-TKIs in EGFR wild-type lung cancer cells both in vitro and in vivo." (PMID 41514577, 2025).
lung cancer (continued). "Lung adenocarcinoma is a common type of lung cancer in Taiwan, where patients often have a unique genetic profile, including a high rate of epidermal growth factor receptor (EGFR) mutations." (PMID 40361443, 2025). "The frequency of such mutations (e.g., targetable EGFR versus KRAS mutations) among lung cancer patients varies by global region and tobacco exposure." (PMID 41479781, 2025). "In the current study, we investigated the impact of BRG1 mutation status on the response of wt-EGFR lung cancer cells to EGFR-TKIs and the associated molecular signaling mechanisms." (PMID 41514577, 2025). "The T790M mutation in EGFR-mutant lung cancer exemplifies this mechanism, conferring resistance to first-generation inhibitors while sensitizing tumors to third-generation agents like osimertinib (OSI)." (PMID 41295218, 2025). "In conclusion, our study underlines the significant impact of EGFR signaling on EV secretion and cargo composition in lung cancer cells." (PMID 40210802, 2025). "Osimertinib, a third-generation epidermal growth factor receptor tyrosine kinase inhibitor, is an effective therapy for epidermal growth factor receptor–mutated non–small cell lung cancer, but it has been associated with a higher incidence of cardiotoxicity." (PMID 40750174, 2025). "Lung adenocarcinoma (LUAD) is the most prevalent form of lung cancer and has been found to have multiple somatic mutations in kinase genes, among which EGFR is the most prevalent, that are treated with tyrosine kinase inhibitor (TKI) therapy." (PMID 40634781, 2025). "One of them used an immunotoxin (saporin) conjugated to cetuximab, an Epidermal Growth Factor Receptor (EGFR) inhibitor, causing cell death, inhibiting recurrence, and increasing antitumor cytotoxicity for the treatment of lung cancer." (PMID 40943508, 2025). "The associations between lipid levels and the incidence of EGFR-mutated lung cancer have rarely been examined in cohort studies." (PMID 39883280, 2025). "EGFR (epidermal growth factor receptor) mutation is common in lung cancer, particularly among young people, women, and those of Asian descent." (PMID 40078313, 2025). "Our meta‐analysis underscores that metastatic behavior in lung cancer was significantly influenced by four pivotal determinants: age, pathological subtypes, EGFR mutations, and treatment modalities." (PMID 40650339, 2025). "A study from Ghana had only 4 of 90 patients with lung cancer tested for EGFR mutation and 2 of those had an EGFR mutation." (PMID 40112503, 2025). "IHC analysis showed that RBM10 expression was associated with brain metastasis in lung cancer patients with EGFR mutations; the low expression group had a higher rate of brain metastasis." (PMID 40069781, 2025). "When integrated with EGFR mutation analysis, it provides robust support for the precise diagnosis and treatment of lung cancer as well as personalized drug therapy." (PMID 41156384, 2025). "The association between East Asian ancestry and EGFR mutation status is consistent with the well-known observation of comparatively high EGFR mutations in lung cancer in this population." (PMID 41162424, 2025). "In lung cancer, clinical practice guidelines have already incorporated the use of liquid biopsy for the detection of the Epidermal Growth Factor Receptor (EGFR) T790M mutation in ctDNA, which will determine treatment follow-up." (PMID 40361366, 2025). "The association between SMARCB1 and EGFR significantly influenced lung cancer cell sensitivity to EGFR-TKI-afatinib, evident in both in vitro and in vivo settings." (PMID 39971779, 2025). "Erlotinib and gefitinib are first and second-line therapies for non-small cell lung cancer, especially for lung cancer with metastatic EGFR mutation positive." (PMID 40216815, 2025).